DUSP9 (dual specificity phosphatase 9)
Description:
Inactivates MAP kinases. Has a specificity for the ERK family.
Synonyms: MKP-4; MKP4
Tractability: PROTAC: ubiquitination databases record sites on it.
Gene: Protein-coding gene on chromosome X (153,642,401 to 153,651,326, forward strand). Ensembl gene ENSG00000130829.
Subcellular location: Cytoplasm
Subcellular location (Human Protein Atlas): Endoplasmic reticulum
Pathways (Reactome):
Signal Transduction: Negative regulation of MAPK pathway; RAF-independent MAPK1/3 activation
Disease: Signaling by MAPK mutants
Gene Ontology:
Molecular function: protein binding; MAP kinase tyrosine phosphatase activity; MAP kinase tyrosine/serine/threonine phosphatase activity; phosphoprotein phosphatase activity; protein tyrosine/serine/threonine phosphatase activity; protein tyrosine/threonine phosphatase activity; protein serine/threonine phosphatase activity; protein tyrosine phosphatase activity
Biological process: ERK1 and ERK2 cascade; JNK cascade; MAPK cascade; negative regulation of ERK1 and ERK2 cascade; protein dephosphorylation
Cellular component: cytoplasm; cytosol; nucleus
Homologues: Orthologues: chimpanzee DUSP9 (99% identical), macaque DUSP9 (98% identical), pig DUSP9 (92% identical), dog DUSP9 (91% identical), rabbit DUSP9 (90% identical), mouse Dusp9 (85% identical), rat Dusp9 (83% identical), tropical clawed frog dusp9 (61% identical), guinea pig DUSP9 (59% identical). Paralogues in human: DUSP7 (55% identical), DUSP6 (55% identical), DUSP2 (29% identical), DUSP5 (28% identical), DUSP1 (28% identical), DUSP4 (28% identical), DUSP8 (27% identical), DUSP10 (26% identical), DUSP16 (26% identical), SSH1 (25% identical), SSH2 (24% identical), SSH3 (23% identical), and 19 more.
Diseases named in the same sentence as DUSP9 in open-access papers:
DUSP9 is named in the same sentence as 61 diseases in open-access papers, as found by Europe PMC text mining. Sharing a sentence is not in itself a finding about the gene and the disease. The quoted sentences say what the papers report.
Insulin resistance (26 papers, 2010 to 2025). Increased resistance towards insulin, that is, diminished effectiveness of insulin in reducing blood glucose levels. "More specifically, PTPs such as PTPN1, PTPN2, PTPN9, PTPN11, PTPRF, and DUSP9 are associated with the pathogenesis of type 2 diabetes, as they negatively modulate insulin signaling and induce insulin resistance." (PMID 35409287, 2022). "Although the DUSP9 locus is considered an important locus for conferring susceptibility to insulin resistance, the contribution of this locus to type 2 diabetes susceptibility in the Japanese population has not yet been evaluated." (PMID 23029454, 2012). "Increased methylation of a gene’s promoter is known to induce gene silencing, and thus increased methylation of the DUSP9 gene could act as a risk factor for insulin resistance and T2DM." (PMID 35330453, 2022). "The recently discovered T2D susceptibility gene, DUSP9, is another gene which could be important to insulin resistance." (PMID 23251491, 2012). "A protective effect against gestational diabetes is also debated, as DUSP9 affects insulin resistance and generally has a complex role in insulin signaling, glucose uptake, and related metabolic processes." (PMID 40564984, 2025). "In the adrenal gland, elevated levels of DUSP9, a key modulator of MAPK signaling linked to cellular stress and insulin resistance, suggest a role in regulating stress-related signaling and metabolic processes." (PMID 40969342, 2025). "Several protein tyrosine phosphatases (PTPs), particularly PTPN1, PTPN2, PTPN6, PTPN9, PTPN11, PTPRS, and DUSP9, are involved in insulin resistance." (PMID 37374154, 2023). "DUSP9/MKP4 is dual-specificity MAP kinase phosphatase that dephosphorylates/inactivates crucial mediators of stress-induced insulin resistance." (PMID 35723340, 2022). "The overexpression of DUSP9/MKP4 clearly protects against stress-induced insulin resistance, in the mice liver, it decreases expression of gluconeogenic genes." (PMID 35723340, 2022). "This SNP is located in an intron of DUSP9 (MKP4), a gene that codes for a phosphatase whose overexpression specifically protects against stress-induced insulin resistance." (PMID 33875891, 2021). "Some PTPs, such as PTPN1, PTPN9, PTPN11, PTPRF, PTPRS, and dual specificity phosphatase 9 (DUSP-9), lead to type 2 diabetes associated insulin resistance through antagonism of insulin action." (PMID 33799458, 2021). "Overall, these data identified DUSP9 as a key regulator of insulin signaling and highlighted its potential role in insulin resistance and metabolic diseases by dephosphorylating kinases involved in metabolic processes, glucose uptake and storage." (PMID 34768967, 2021). "Enhanced DUSP9 expression has a protective effect against the development of insulin resistance by counteracting the effects of proinflammatory cytokines, such as TNF-α." (PMID 33192474, 2020). "Polymorphisms in the human DUSP9 gene were repeatedly associated with increased risk for diabetes in genome-wide association studies (GWAS), consistent with a protective function of DUSP9 in the development of insulin resistance in a transgenic mouse model." (PMID 31159473, 2019). "On the other hand, studies have suggested that DUSP9 can inhibit insulin resistance by acting as a MAPK phosphatase and influencing downstream signaling factors of the MAPK pathway, such as ERK, JNK, and p38." (PMID 31772940, 2019). "But there is still possibility that DUSP9 upregulation was the results of insulin resistance and/or hyperglycemia." (PMID 31772940, 2019). "Previous studies have shown a protective role for Dusp-9 against insulin resistance through inhibition of stress-activated kinases (SAPs)." (PMID 20307313, 2010).
Insulin resistance (continued). "Compared with DUSP9, PTPN9 knockdown resulted in a greater increase in AMPK phosphorylation, while Brice Emanuelli showed that DUSP9 has a protective effect on insulin resistance by dephosphorylating EAK and JNK, which have been shown to induce insulin resistance." (PMID 35409287, 2022). "Another phosphatase family member, dual-specificity phosphatase-9 (DUSP-9), also known as MKP4, is also proven to be involved in insulin resistance due to its expression in insulin-sensitive tissues and the modulation of DUSP-9 expression in insulin-resistant states." (PMID 36558920, 2022). "This raises the question of the role of DUSP9 as an effector of gestational insulin resistance." (PMID 34768967, 2021). "The first report of a link between DUSP9 and insulin resistance was published in 2003." (PMID 34768967, 2021). "Studies have suggested that DUSP9 promotes obesity-related insulin resistance; in adipocytes, DUSP9 may promote insulin resistance by inhibiting insulin-stimulated differentiation and glucose uptake." (PMID 31772940, 2019). "DUSP9 upregulation in the placenta of GDM pregnant women may promote insulin resistance, which may correlate with the occurrence of GDM." (PMID 31772940, 2019). "Our results suggest that DUSP9 upregulation in the placenta of GDM pregnant women may promote insulin resistance by acting as a MAPK phosphatase and influencing downstream signaling factors of the MAPK pathway, which may correlate with the occurrence of GDM." (PMID 31772940, 2019). "DUSP9 regulates insulin resistance by affecting IRS-1-related signaling pathways." (PMID 31772940, 2019). "We hypothesize that DUSP9 upregulation in trophoblast cells promotes insulin resistance in the pathogenesis of GDM." (PMID 31772940, 2019). "In contrast, decreased Dusp-9 can lead to insulin resistance." (PMID 20307313, 2010). "In addition, in the clinical factors analysis, we found that DUSP9 expression was higher in patients with a history of diabetes than in those without, which may be related to the role of DUSP9 in insulin resistance." (PMID 40861803, 2025). "Importantly, DUSP9 can impede insulin resistance in vivo in the ob/ob murine model by lowering blood glucose levels and by restoring the normal level of enzymes involved in gluconeogenesis and lipogenesis such as fructose-1,6-biphosphatase, SREBP1C, SCD1 and ACC." (PMID 34768967, 2021). "There are conflicting opinions on whether DUSP9 promotes or inhibits insulin resistance." (PMID 31772940, 2019). "DUSP9 may inhibit insulin resistance by antagonizing the effects of tumor necrosis factor-α." (PMID 31772940, 2019). "However, DUSP9/MKP-4 is essential for placental development and has been linked to obesity, insulin resistance and type 2 diabetes in both murine models and human GWAS studies, highlighting the study of DUSP9/MKP-4 modification in relevant disease models as a key area of investigation." (PMID 22812510, 2013). "One of these genes is the Dual Specificity Phosphatase 9 (DUSP9) gene, which is protective against insulin resistance and which exhibited a higher percentage of methylation in female pancreatic islets." (PMID 35330453, 2022). "Moreover, DUSP9 can also impair the action of extracellular mediators and stress inducers (i.e., proinflammatory cytokines, oxidative compounds, endoplasmic reticulum stress effectors), which can induce insulin resistance by abnormally activating MAPK or SAP pathways." (PMID 34768967, 2021). "For instance, by inhibiting the canonical JNK phosphorylation, DUSP9 contributes to the fine-tuning of JNK, finally amending glucose intolerance and repressing hepatic steatosis in stress-induced insulin resistance." (PMID 34239349, 2021). "In 2004, Bazuine and collaborators demonstrated the negative role of DUSP9 in induced insulin resistance through an alternative phosphorylation cascade governed by p38 MAPK." (PMID 34768967, 2021).
Insulin resistance (continued). "Interestingly, this insulin resistance-induced down-regulation of DUSP9 occurred at the protein level but not at the transcript level, suggesting the translational regulation and/or the potential implication of miRNAs." (PMID 34768967, 2021). "DUSP9 over-expression in genetically obese ob/ob mice on the other hand, improved glucose tolerance, while DUSP9 over-expression in 3T3-L1 adipocytes suppressed ERK1/2 and JNK activation, with a concomitant reduction in IRS1 serine phosphorylation that prevented the induction of insulin resistance." (PMID 25375135, 2014). "However, since DUSP9 plays a negative role in induced insulin resistance, the significant inhibition of DUSP9 in the long term may induce insulin resistance in target cells." (PMID 35409287, 2022).
type 2 diabetes (14 papers, 2012 to 2025). "We also examined two genes in more depth, DUSP9, which is associated with type 2 diabetes, and G6PD, which is associated with type 2 diabetes and is causal for G6PD deficiency." (PMID 41286645, 2025). "More broadly, many GWAS in different ethnic groups have identified DUSP9 as a susceptibility gene for type 2 diabetes mellitus." (PMID 31772940, 2019). "Several genome-wide association studies have identified DUSP9 as a susceptibility gene for type 2 diabetes mellitus, in particular the DUSP9 rs5945326 polymorphism." (PMID 31772940, 2019). "Among the examined SNP loci in the present study, we found that rs5945326 near DUSP9 on the X chromosome was strongly associated with type 2 diabetes in the Japanese population." (PMID 23029454, 2012). "Of these, 1 SNP, rs5945326 near DUSP9, was significantly associated with type 2 diabetes, and the association reached a genome-wide significance level (p<5×10−8)." (PMID 23029454, 2012). "One SNP, rs5945326 near DUSP9, was significantly associated with type 2 diabetes at a genome-wide significance level (p = 2.21×10−8; OR 1.39, 95% confidence interval [CI]: 1.24−1.56)." (PMID 23029454, 2012). "An expanded meta-analysis of the existing European GWAS data (DIAGRAM+: Diabetes Genetics Replication and Meta-analysis+) has identified 12 loci, including 11 autosomal loci and the DUSP9 locus on chromosome X, as a strong susceptibility locus for type 2 diabetes." (PMID 23029454, 2012). "The DUSP9 locus on chromosome X was identified as a susceptibility locus for type 2 diabetes in a meta-analysis of European genome-wide association studies (GWAS), and GWAS in South Asian populations identified 6 additional single nucleotide polymorphism (SNP) loci for type 2 diabetes." (PMID 23029454, 2012). "Given that the parent study was a genetic epidemiology study of type 2 diabetes, we explored the implications of XCI for DUSP9, the chromosome X gene most strongly associated with type 2 diabetes." (PMID 41286645, 2025). "Diverse PTPs, such as PTPN1, PTPN2, PTPN9, PTPN11, PTPRS, and DUSP9, have been reported to attenuate insulin signaling and trigger type 2 diabetes, indicating that PTPs are promising drug targets for the treatment or prevention of type 2 diabetes." (PMID 35204821, 2022). "Some PTPs, such as PTPN1, PTPN2, PTPN9, PTPN11, PTPRS, and DUSP9, have been shown to attenuate insulin signaling and trigger type 2 diabetes, indicating that PTPs are promising drug targets for the treatment or prevention of type 2 diabetes." (PMID 35204821, 2022). "Several PTPs, such as PTPN1, PTPN2, PTPN9, PTPN11, PTPRS, and DUSP9, disrupt insulin signaling and trigger type 2 diabetes, indicating that PTPs are promising drug targets for the treatment or prevention of type 2 diabetes." (PMID 35204821, 2022). "Results from other investigations indicate that DUSP9 and SLC30A8 are common susceptibility loci for type 2 diabetes across various ethnicities." (PMID 24098730, 2013). "Sites annotated to 10 candidate genes for type 2 diabetes, including DUSP9, BCL11A, HNF4A, and CDKN2B, and 7 candidate genes for related metabolic traits (for example, ATP11A, ADCY5 and IRS1) had differential DNA methylation in human pancreatic islets based on sex." (PMID 25517766, 2014). "Finally, a recent study reported that higher expression of DUSP9 in placental cytotrophoblasts is associated with hyperglycemia in pregnant women suffering from type 2 diabetes mellitus compared to pregnant women not presenting it." (PMID 34768967, 2021). "We explored the implications of XCI with respect to DUSP9 and G6PD in the context of type 2 diabetes." (PMID 41286645, 2025). "Several protein phosphatases, such as PTPN9, DUSP9, and PTPN11, have been identified as AMPK-related targets for type 2 diabetes." (PMID 35563411, 2022).
type 2 diabetes (continued). "Therefore, any therapeutic intervention to increase DUSP9 expression or to control the activity of ERK1/2, JNK, p38 MAPK and/or ASK1 kinases could be beneficial for patients presenting metabolic syndromes such as type 2 diabetes, morbid obesity, liver cirrhosis, NAFLD or its most severe form, NASH." (PMID 34768967, 2021).
Obesity (9 papers, 2010 to 2023). Accumulation of substantial excess body fat. "Using liver-specific murine models, various feeding conditions and genetic gain- and loss-of-function approaches, they showed that the DUSP9 protein level is slowly and steadily decreased in the liver of mice fed on a high fat diet or presenting obesity." (PMID 34768967, 2021). "In conclusion, only five of the 37 genetic variants previously linked to T2DM and obesity in the Saudi Arabian population [HNF4A-rs4812829, WFS1-rs1801214, DUSP9-rs5945326, ZFAND6-rs11634397, FTO-rs11642841] were associated with prediabetes susceptibility." (PMID 36980809, 2023). "As a consequence, DUSP9 plays a major role in human pathologies and more specifically in cardiac dysfunction, liver metabolic syndromes, diabetes, obesity and cancer including drug response and cell stemness." (PMID 34768967, 2021). "Studies reporting roles for the MAPK dual specificity phosphatases DUSP1 and DUSP9 during inflammation, obesity and insulin sensitivity, prompted us to investigate what function DUSP2 might play in these processes." (PMID 25375135, 2014). "This suggests that calorie restriction and obesity may affect insulin sensitivity by affecting the balance of phosphatases such as Dusp-9 and Ptpra." (PMID 20307313, 2010). "We show that the CR increased the expression levels of anti-inflammatory genes Il-10 and Adrbk1 and energy homeostasis-related genes such as Ptgds, Lpin2, Angptl6, Kcnj11, and Dusp9 but were not affected by obesity in HF mice." (PMID 20307313, 2010).
gastric cancer (7 papers, 2019 to 2025). A primary or metastatic malignant neoplasm involving the stomach. "Conversely, DUSP9 downregulation has been noted in clear cell renal carcinoma, gastric carcinoma, and colorectal carcinoma, functioning as a tumor suppressor 11-13." (PMID 40861803, 2025). "In gastric cancer, the low expression of DUSP9 promoted the proliferation of gastric cancer cells by activating the JNK signaling pathway." (PMID 35163786, 2022). "Recently, low expression levels of DUSP9 were reported in a variety of cancers, such as gastric cancer, liver cancer, and renal cancer." (PMID 33072575, 2020). "Accumulating evidence suggests that DUSP9 is downregulated and acts as a tumor suppressor in many kinds of cancers, such as gastric cancer, hepatocellular carcinomas, renal cancer, squamous cell carcinoma (SCC), etc.." (PMID 33072575, 2020). "However, other studies demonstrated that downregulation of DUSP9 promotes tumor progression and contributes to poor prognosis in colorectal cancer, and DUSP9 silencing activates JNK signaling to promote cell proliferation in human gastric cancer." (PMID 34830961, 2021). "In gastric cancer, low expression level of DUSP9 has been found to be linked with the increased JNK activity and decreased apoptosis, suggesting that DUSP9 may inhibit the proliferation of gastric cancer cells through JNK signaling pathway." (PMID 33072575, 2020). "In gastric cancer (GC), the expression level of DUSP9 is low at all stages of the disease and is the lowest in advanced stages." (PMID 34768967, 2021). "MKP-4 also acts as a tumor suppressor gene in many other cancers in addition to HCC and it has been reported that promoter methylation of DUSP9 in human gastric cancer and colorectal cancer is an important reason for its decreased expression." (PMID 30923463, 2019).